MMP9 (matrix metallopeptidase 9)
Diseases named in the same sentence as MMP9 in open-access papers (continued):
Sharing a sentence is not in itself a finding about the gene and the disease.
osteosarcoma (176 papers, 2004 to 2026). A usually aggressive malignant bone-forming mesenchymal neoplasm, predominantly affecting adolescents and young adults. "In support of this evidence, our previously published results demonstrated the elevation of MMP-9 gene and protein in osteosarcoma and Ewing sarcoma tumors that was associated with tumor recurrence and metastasis." (PMID 37993664, 2023). "In support of this, our previously published data showed the over-expression of MMP-9 and its association with tumor recurrence and metastasis of osteosarcoma and Ewing sarcoma." (PMID 36713521, 2022). "Among them, MMP-2 and MMP-9 play a key role in initiating osteosarcoma cell metastasis and associate with poor response to chemotherapy in osteosarcoma." (PMID 34953496, 2021). "Immunohistochemical studies in resection specimens of these patients showed that overexpression of MMP-9 in osteosarcoma cells is significantly associated with metastases and poor overall survival." (PMID 32377334, 2020). "Our results showed that upregulated HMGN5 in a hypoxic environment increased the expression of c-jun and finally increased the expression of MMP2 and MMP9, which was associated with migration and invasion of osteosarcoma." (PMID 31930127, 2019). "Another recent meta-analysis evaluated the prognostic significance of MMP-9 expression for osteosarcoma risk, and found that MMP-9 expression was associated with an increased mortality rate of osteosarcoma during the follow-up research." (PMID 30262739, 2018). "A recent meta-analysis study evaluated the diagnostic value of MMP-9 as a biomarker to osteosarcoma." (PMID 30262739, 2018). "The expression of MMP-2 and MMP-9 is upregulated in osteosarcoma tissue and is associated with pulmonary metastasis and lower overall survival in patients with osteosarcoma." (PMID 30235848, 2018). "The depletion of S100A4 expression results in the reduction of osteosarcoma cell motility and the loss of osteosarcoma cell metastatic potential, which is completely rescued by MMP-9 overexpression." (PMID 29069865, 2017). "Of all MMPs, MMP-2 and MMP-9 are most widely studied that both gain and loss-of function are associated with osteosarcoma progression." (PMID 27144433, 2016). "In stage IIB osteosarcoma, the immunohistochemical status of MMP9 has been shown to be strongly associated with overall and disease-free survival." (PMID 26979530, 2016). "MMP-2 and MMP-9 have been demonstrated to be overexpressed in osteosarcoma and promote lung metastasis, and regulation of these enzymes is associated with other metabolic pathways that are overexpressed in osteosarcoma, including de novo serine biosynthesis." (PMID 33809018, 2021). "Interestingly, high MMP-9 expression is associated with poor prognosis in patients with osteosarcoma in several meta-analysis reports." (PMID 33228783, 2020). "Moreover, MMP-2 and/or MMP-9 expression can be associated with the development of metastasis, poor prognosis and resistance to chemotherapy in osteosarcoma patients." (PMID 31370265, 2019). "All in all, our results support previous work demonstrating that MMP9 is strongly implicated in lung metastasis potential and invasive behavior in osteosarcoma and this may occur in a PC4-dependent manner." (PMID 28881805, 2017). "Based on the results of MCC algorithm scores in Cytoscape, MMP9 ranked highest among those hub genes, suggesting that MMP9 may be the most related gene that caused the progression of osteosarcoma, and it was meaningful to focused on MMP9 for subsequent research." (PMID 34261456, 2021). "This aligns with previous studies reporting that WISP1 promotes MMP2 and MMP9 expression in chondrosarcoma and osteosarcoma cells, thereby facilitating motility and invasion." (PMID 41597235, 2026). "The elevated activity of these type IV collagenases (MMP-2 and MMP-9) is recognized as a key contributor to tumor progression and dissemination in several malignancies, including osteosarcoma." (PMID 40869275, 2025).
osteosarcoma (continued). "Evidence from previous studies suggests that MAPK15 facilitates osteosarcoma invasion cell migration via modulation of MMP-9 expression." (PMID 39866235, 2025). "Upregulation of MMP9 by activation of the PI3K/AKT pathway has been demonstrated to promote osteosarcoma migration." (PMID 40779492, 2025). "Elevated EMP1 expression in osteosarcoma tissues is closely associated with lymphatic and distant metastasis, stimulating malignant progression via the IRX2/MMP9 axis." (PMID 40612666, 2024). "For example, CAFs expressing MMP-2 and MMP-9 have been identified in osteosarcoma, and their increased presence in the tumor area has been associated with MMP-2 and MMP-9 expression." (PMID 38542199, 2024). "They summarized the effect of a comprehensive assessment of the effect of high MMP-9 expression on survival outcomes in patients with osteosarcoma and found that patients with high MMP-9 expression had significantly lower overall survival." (PMID 36814819, 2023). "Relaxin is a short circulating peptide hormone, which decreases the in vitro invasive ability in osteosarcoma MG-63 cells by reducing the level of MMP-9." (PMID 37007044, 2023). "Adding to this intricate dynamic is CREB3, a member of the leucine zipper transcription factor lineage, which can intimately bind the c-Jun promoter, thereby steering osteosarcoma evolution through genes like MMP9 and Bcl-2." (PMID 38140058, 2023). "Activated by CERB3, c-Jun upregulates MMP9 and Bcl-2 to promote osteosarcoma proliferation and metastasis." (PMID 37197432, 2023). "Decitabine exposure in osteosarcoma reduces the protein expression of the metastasis-associated markers VIMENTIN, SLUG, ZEB1, and MMP9, with a concurrent decrease in mRNA expression of the known stem cell markers SOX2, OCT4, and NANOG." (PMID 37197432, 2023). "In our work, the degradation of the here used Mg-based materials led to an increased secretion of MMP-2 and MMP-9 and suggested an increased invasion and metastatic capability of osteosarcoma cells under the impact of those materials." (PMID 35600975, 2023). "Altogether, these results suggest that aprepitant can modulate the invasive behavior of human osteosarcoma cells, possibly by regulating both the expression and activities of MMP-9 and MMP-2." (PMID 36177059, 2022). "In the study, by the method of bioinformatics analysis, the possible key genes of osteosarcoma including MMP9, FERMT3, CSF1R, and VWF were screened from two microarray datasets, GSE12865 and GSE36001." (PMID 35814015, 2022). "Through the comprehensive integration of GO, KEGG pathway analysis, and Cytoscape software analysis results, four osteosarcoma key genes, MMP9, FERMT3, CSF1R, and VWF, were finally identified." (PMID 35814015, 2022). "According to research, STK39 dysregulation affects MMP2 (matrix metallopeptidase 2) and MMP9 (matrix metallopeptidase 9), thus actively participating in osteosarcoma." (PMID 36005137, 2022). "Many studies have used MMP-9 as a regulatory factor for evaluating tumour invasion and metastasis (including osteosarcoma)." (PMID 35264209, 2022). "Accordingly, blockage of IGF-1R caused down-regulation of matrix metalloproteinase-2 (MMP-2) and MMP-9 and suppress migration of human osteosarcoma (OS) MG-63 cells." (PMID 36713521, 2022). "Wogonin induces apoptosis in the CSCs of human osteosarcoma cells (CD133-positive osteosarcoma cells), inhibits its mobility in vitro via downregulation of MMP-9 expression, and represses its self-renewal ability." (PMID 34884848, 2021). "MMP-2 and MMP-9 are highly expressed in osteosarcoma tissues, and they play important roles in the invasion and metastasis of tumor cells." (PMID 33969873, 2021). "This study aimed to identify novel targets in the carcinogenesis, therapy and prognosis of osteosarcoma from genomic level, together with screening ideal lead compounds with potential inhibition regarding MMP-9." (PMID 34261456, 2021).
osteosarcoma (continued). "This study elucidated the procedure from identification of hub genes in osteosarcoma, to the study of inhibitors targeting MMP9 in detail, each step was clearly explained." (PMID 34261456, 2021). "While in osteosarcoma, a predominant MMP-2/MMP-9 activity is associated with poor response to chemotherapy." (PMID 35047406, 2021). "Meanwhile, this study made an overall evaluation of expression pattern of MMP9 in different cancer, and filled up the gap in research of MMP9 in osteosarcoma." (PMID 34261456, 2021). "Among them, MMP9 ranked highest, suggesting that MMP9 was the most related gene in the development of Osteosarcoma, then this study further focused on MMP9 to find potential inhibitors in structural biology part." (PMID 34261456, 2021). "The in vitro results in the current study showed that MCP-1 contributes to cancer cell migration by inducing MMP-9 expression in osteosarcoma cells." (PMID 33228783, 2020). "In the present study, we found that MCP-1 exhibit metastasis-promoting roles by increasing MMP-9 expression in osteosarcoma." (PMID 33228783, 2020). "This signal pathway regulated AP-1 activation and MMP-9 transcription, which further upregulated osteosarcoma migration." (PMID 33228783, 2020). "The present study demonstrates that MCP-1 regulates cell mobility through matrix metalloproteinase (MMP)-9 expression in osteosarcoma cells." (PMID 33228783, 2020). "Studies have revealed that MEK, ERK, JNK, and p38 MAPK play crucial roles in MMP-9 regulation and osteosarcoma metastasis." (PMID 33228783, 2020). "We therefore examined the effect of integrin ανβ3 neutralizing antibody to investigate the effect of integrin ανβ3 neutralization in TSP‐2‐induced stimulation of osteosarcoma cell migratory potential and MMP‐9 expression." (PMID 33021341, 2020). "According to these results, MCP-1 induced MMP-9 expression and cell migration through the c-Raf signaling pathway in osteosarcoma." (PMID 33228783, 2020). "In summary, integrin αvβ3 effectively modulates TSP‐2‐induced MMP‐9 expression and migratory potential in osteosarcoma cells." (PMID 33021341, 2020). "To confirm these findings, we examined the expressions of MCP-1 and MMP-9 in different-stage osteosarcoma cells as well as in normal human bone tissue." (PMID 33228783, 2020). "When osteosarcoma cells were treated with MMP-9 monoclonal antibody (mAb), the degree of cell migration significantly decreased." (PMID 33228783, 2020). "Our results also suggest that TSP‐2 potentiates MMP‐9 expression in human osteosarcoma cells and their mobility by regulating the integrin αvβ3/PLC/PKC/c‐Src/NF‐kB signalling transduction pathway." (PMID 33021341, 2020). "We also found positive correlation between MCP-1 and MMP-9 in migration-prone subclones of osteosarcoma as well as in tumor tissue array of osteosarcoma patients." (PMID 33228783, 2020). "The expression patterns of TSP‐2 and MMP‐9 were also similar amongst osteosarcoma cell lines and normal osteoblast, with greatest expression in HOS cells." (PMID 33021341, 2020). "Osteosarcoma cells overexpress the very important metalloproteinase, MMP-9 (also known as gelatinase-B) that helps them to invade and metastasize." (PMID 32377334, 2020). "MCP-1-promoted osteosarcoma cell migratory ability remarkably decreased after MMP-9 siRNA pretreatment." (PMID 33228783, 2020). "PTEN inhibits proliferation, migration, and invasion in osteosarcoma cells by downregulating MMP9 and focal adhesion kinase (FAK)." (PMID 32986377, 2020). "Studies have revealed that MMPs such as MMP-2, MMP-3, and MMP-9 are involved in osteosarcoma progression and metastasis." (PMID 33228783, 2020). "The tissue array results revealed that higher concentrations of MCP-1 and MMP-9 were produced as the high grade of osteosarcoma increased." (PMID 33228783, 2020).
osteosarcoma (continued). "It appears that an interaction between TSP‐2 and integrin αvβ3 activates the PLCβ, PKCα and c‐Src signalling pathways and subsequently activates NF‐κB signalling, increasing MMP‐9 expression and stimulating migratory activity amongst human osteosarcoma cells." (PMID 33021341, 2020). "Studies have shown that the block Human MMP9 NF-κB binding site can inhibit the mobility of Human Osteosarcoma Cell." (PMID 31110076, 2019). "It was indeed reported that inhibiting this pathway decreases both the MMP2 and the MMP9 activities, further impeding the metastatic spreading of the murine Osteosarcoma cell line LM8, nevertheless highly aggressive." (PMID 30515265, 2018). "Studies have shown that ECM degradation mediated by MMP-2 and MMP-9 plays a critical role in the motility and invasiveness of osteosarcoma cells." (PMID 30235848, 2018). "In osteosarcoma, studies indicated that the repression of MMP-2 and MMP-9 decreases the ability of osteosarcoma cells to migrate and invade." (PMID 30235848, 2018). "In this analysis, pooled sensitivity, pooled specificity and DOR of MMP-9 for osteosarcoma were found to be 0.78 (95% confidence interval CI: 0.730–0.83), 0.90 (95% CI: 0.79–0.95) and 31.20 (95% CI: 11.97–81.31), respectively." (PMID 30262739, 2018). "In the current study, knockdown of DRP5 resulted in a remarkable downregulation of MMP‐2 and MMP‐9, which was consistent with the reduced numbers of osteosarcoma cells with migratory and invasive activities." (PMID 28374915, 2017). "Taken together, these clinical evidences state that MMP-9 is essential for tumor metastasis which makes osteosarcoma become more risky instead of its usual localization." (PMID 28606135, 2017). "A reporter gene assay demonstrated that BITC, PEITC, and SFN suppressed TAP-induced MMP-9 expression by inhibiting AP-1 and NF-κB in U20S osteosarcoma cells." (PMID 28969043, 2017). "And MMP-2 and MMP-9, two of the major proteases, which contribute to migration and invasion in osteosarcoma pathogenesis." (PMID 29156780, 2017). "Our study demonstrated that Wogonin, a compound extracted from S. baicalensis, targets the invasion of osteosarcoma CSC through MMP-9 suppression." (PMID 28606135, 2017). "In this study, we found a pronounced suppressive effect of glucosamine sulfate particularly on MMP-3 and also MMP-9 mRNA and protein levels in osteosarcoma cell lines in vitro." (PMID 27562075, 2016). "HOTAIR is commonly overexpressed in osteosarcoma, and its knockdown significantly inhibits cellular proliferation and invasion by decreasing MMP-2 and MMP-9 section in osteosarcoma cells." (PMID 27685633, 2016). "Lower levels of the osteosarcoma metastasis-associated proteins CXCR4, MMP-2, MMP-7 and MMP-9 were detected in siEZH2 cells." (PMID 26265454, 2015). "More recently, silencing the expression of ANGPTL2 in osteosarcoma cell lines delayed the occurrence of lung metastases when injected in nude mice by reducing the expression of MMP9." (PMID 25360865, 2015). "Deguelin significantly inhibited migration and invasion of U-2 OS human osteosarcoma cells which was associated with a reduction of activities of matrix metalloproteinases-2 (MMP-2) and matrix metalloproteinases-9 (MMP-9)." (PMID 25322282, 2014). "Analysis revealed a positive correlation between u-PA and MMP-2 expressions of NM-treated osteosarcoma MNNG-HOS and between u-PA and MMP-2 and MMP-9 expressions of osteosarcoma U-2OS and rhabdomyosarcoma RD, as shown inTable II." (PMID 23900236, 2013). "MMP-2 and MMP-9 are overexpressed in osteosarcoma and promote osteosarcoma cell migration and invasion by degrading certain components of the basement membrane and epimatrix." (PMID 23946787, 2013). "Our study evaluated serum alkaline phosphatase (ALP) cooperating with matrix metalloproteinase-9 (MMP-9) as an important prognostic predictor for local recurrence and distant metastasis of osteosarcoma." (PMID 22333159, 2012).
osteosarcoma (continued). "The positive rate and index of MMP-9 expression in osteosarcoma tissues were highest in very high pre-ALP group." (PMID 22333159, 2012). "Only a few previous studies have studied the ALP levels in osteosarcoma patients after chemotherapy and surgery or cases of local recurrence or lung metastasis after surgery, or have considered MMP-9 expression in these contexts." (PMID 22333159, 2012). "In summary, the current study demonstrates the level of ALP is an independent prognostic factor for the survival of osteosarcoma patients, and is correlated with MMP-9 expression in osteosarcoma tissues." (PMID 22333159, 2012). "Pre-ALP was an independent prognostic factor for the survival of osteosarcoma patients in south China, and correlated with MMP-9 expression and lung metastasis." (PMID 22333159, 2012). "Accordingly, our findings demonstrate that risedronate has anti-invasive and antimetastatic activity via the inhibition of MMP-2 and MMP-9 activity in human osteosarcoma cells." (PMID 19624845, 2009). "This study suggests that risedronate downregulates the expressions of MMP-2 and MMP-9 in osteosarcoma, and that this is responsible for its effect on osteosarcoma cell invasiveness." (PMID 19624845, 2009). "Perissinotto reported that CXCL12 can markedly upregulate the expression and activity of MMP-9 in osteosarcoma." (PMID 18983683, 2008). "DSF has been shown to reduce MMP9 expression and activity in osteosarcoma cells." (PMID 40170735, 2025). "Valproic acid decreases the expression of MMP2 and MMP9 mRNAs in osteosarcoma cells." (PMID 39253583, 2024). "MMP-2, MMP-7, MMP-9, and MMP-14 have been linked to the progression and metastasis of osteosarcoma." (PMID 38816365, 2024). "Yue further demonstrated that knocking down ERK5 in osteosarcoma cell lines could enhance Slug signaling and MMP-9 expression, thereby reducing tumor cell migration and invasion." (PMID 38785963, 2024). "Moreover, upregulated miR-124 significantly suppresses cell proliferation, invasion, and downregulates levels of MMP2 and MMP9 among osteosarcoma cells." (PMID 35184134, 2022). "MMP-9 is highly expressed in osteosarcoma, in our study, MMP-9 expression was down-regulated after CD44 was knocked down, reflecting the promoting effect of CD44 on invasion and metastasis of osteosarcoma cells, which is consistent with the role of CD44 in other tumours." (PMID 35264209, 2022). "We also examined whether aprepitant could influence the gelatinase activities of MMP-2 and MMP-9 in the MG-63 osteosarcoma cell line." (PMID 36177059, 2022). "Furthermore, MMP-2 and MMP-9 have been found as potential therapeutic targets in different tumor types as well as osteosarcoma." (PMID 36177059, 2022). "In addition, we previously found that high Siglec-15 levels in osteosarcoma were associated with lung metastasis of osteosarcoma and promoted the viciousness of osteosarcoma cells and enhanced the EMT and MMP-9 levels in vitro and in vivo." (PMID 36290882, 2022). "It has also been shown that MCP-1 induces osteosarcoma metastasis by MMP-9 overexpression." (PMID 35455040, 2022). "In addition, the proteolytic activity of MMP-9 in osteosarcoma induced the cleavage of MICA on the surface of cancer cells." (PMID 34502191, 2021). "In addition, western blotting revealed that the expression levels of MMP-2 and MMP-9 were decreased in osteosarcoma cells treated with both cordycepin and cisplatin for 48 h compared to those in the control group and those treated with either drug alone." (PMID 34953496, 2021). "Both MMP8 and MMP9 were produced by osteoclasts in osteosarcoma tissue." (PMID 34811438, 2021). "Furthermore, upstream PI3K/Akt and ERK signaling pathways upregulate MMP2 and MMP9 expression, thus enabling osteosarcoma invasion and metastasis." (PMID 35145908, 2021). "Meanwhile, researches based on MMP9 inhibitors regarding osteosarcoma had hardly been reported before, which could make significance in targeted chemotherapy regarding osteosarcoma." (PMID 34261456, 2021).